KRT88P (keratin 88, pseudogene)
Synonyms: HBC; formerly KRTHBP3; KRT122P
Gene: Unprocessed pseudogene on chromosome 12 (52,263,948 to 52,267,540, forward strand). Ensembl gene ENSG00000284883.
Diseases named in the same sentence as KRT88P in open-access papers:
KRT88P is named in the same sentence as 143 diseases in open-access papers, as found by Europe PMC text mining. Sharing a sentence is not in itself a finding about the gene and the disease.
KRT88P shares sentences with these, for which no sentence is quoted: infection (347 papers); hepatitis B (165); Hepatitis (93); chronic hepatitis B (51); hepatocellular carcinoma (42); liver disease (40); malaria (38); cancer (26); co-infection (24); tumor (22); syphilis (18); thalassemia (17); viral infection (17); Cirrhosis (14); viral hepatitis (14); hematological malignancies (13); hepatitis C (13); anemia (11); liver cirrhosis (11); sickle cell disease (11); Acute hepatitis (10); lymphoma (10); chronic hepatitis (9); Hepatic fibrosis (9); influenza (9); liver cancer (9); diabetes (8); hemoglobinopathies (8); acute liver failure (6); fibrosis (6).
A further 113 diseases each share a sentence with KRT88P in 6 papers or fewer.